ID1 (inhibitor of DNA binding 1)
Diseases named in the same sentence as ID1 in open-access papers (continued):
Sharing a sentence is not in itself a finding about the gene and the disease.
lung carcinoma (continued). "In previous studies, ID1 was shown to participate in liver metastasis of lung cancer cells through EMT and knockout of ID1 may lead to decreased expression of vimentin, TGF-β and Snail." (PMID 33992097, 2021). "In addition, ID1 is predominantly expressed in lung cancer cells and is directly regulated by PGC1α at the transcriptional level." (PMID 33917757, 2021). "PGC1α expression revealed a strong correlation with ID1 in lung cancer tissues." (PMID 33917757, 2021). "IHC results also revealed the low expression of PGC1α and ID1 in primary lung cancer (PLC)." (PMID 33917757, 2021). "Consistently with our findings, PGC1α and ID1 is expressed at a low level in lung cancer." (PMID 33917757, 2021). "In addition, 3 out of 26 major cancers (breast, ovarian, and lung cancers) expressed PGC1α and ID1 at a lower level in the TCGA dataset." (PMID 33917757, 2021). "We found that PGC1α not only promotes ID1, but also ID2 and ID3 expression in lung cancer cells, suggesting that PGC1α-mediated expression of ID families might be dependent on the cellular context and transcription factors, which are activated by PGC1α." (PMID 33917757, 2021). "Previous studies have also reported that ID1 is highly expressed in lung cancer cells." (PMID 33992097, 2021). "Since ID1 is predominantly expressed in lung cancer among the ID family, we reasoned that ID1 serves as an important factor in the loss of PGC1α-driven EMT and propose that PGC1α acts as a transcriptional regulator of ID1 expression." (PMID 33917757, 2021). "Therefore, the present results suggested that low mRNA expression level of ID1 or high mRNA expression levels of ID2/3/4 predicted an improved survival in patients with lung cancer." (PMID 32003423, 2020). "Therefore, patients with lung cancer with a low mRNA expression level of ID1 or high mRNA expression levels of ID2/3/4 were predicted to have longer OS, FP and PPS." (PMID 32003423, 2020). "Although baicalein has numerous purported properties, the link to Id1 activity in lung cancer is still unknown." (PMID 30949224, 2019). "In the current study, our purpose was to determine whether baicalein was active against Id1 in orthotopic lung cancer model." (PMID 30949224, 2019). "The anti-chemo-resistant role of ID1 has been revealed in prostate cancer and lung cancer." (PMID 30154433, 2018). "Western blot and qRT-PCR were used to quantify the expression of ID1 in lung cancer." (PMID 27978873, 2016). "In addition, paclitaxel treatment of A549, H460, and H520 lung cancer cells suppressed Id1 expression in a dose-dependent manner." (PMID 25344919, 2014). "As Id1 was known to promote Akt activation via phosphorylation in lung cancer and other caner types, we also examined whether treatment of paclitaxel and cisplatin affected the expression level of phosphorylated Akt." (PMID 25344919, 2014). "An increased level of Id1 expression in lung cancer tissues was positively correlated with the increased tumor size (4.54±0.24 cm of the tumor in the high Id1 expression group vs. 3.70±0.24 cm of the tumor in the low Id1 expression group; P = 0.022)." (PMID 25344919, 2014). "We conclude that Id1, as a mediator of tumor cell migration, may be an indicator of aggressive potential in nonsmall-cell lung cancers." (PMID 20414347, 2010). "Thus, we speculate that cooperation between FOXA1 and PGC1α may participate in EMT-related gene expression by regulating ID1 expression in lung cancer cells." (PMID 35897813, 2022). "Thus, our findings demonstrate that FOXA1 and PGC1α-mediated transcriptional regulation of ID1 expression may involve energy metabolism in metabolic tissues as well as lung cancer metastasis." (PMID 35897813, 2022).
lung carcinoma (continued). "We also found that ID1 is highly expressed in lung cancers among other ID proteins, which was confirmed in vitro, by using bioinformatics and analysis via the publicly available TCGA dataset; thus, these results led us to hypothesize that ID1 played a crucial role in PGC1α loss-induced EMT." (PMID 33917757, 2021). "Based on our results, we suggest that ID1 is predominantly involved in EMT in lung cancer metastasis and speculate that the differential expression levels of ID1 between the cytoplasm and the nuclei might distinguish between the oncogenic or tumor suppressive role of ID1." (PMID 33917757, 2021). "As ID1 and TWIST1 share the binding domain of TCF4, PGC1α knock down-driven ID1 loss could not interfere with the TCF4-TWIST1 complex, and thus, induced EMT potential in the process of lung cancer metastasis." (PMID 33917757, 2021). "Next, we examined whether Id1 and/or Id3 regulates cell survival and growth of lung cancer cells." (PMID 23593444, 2013). "Furthermore, among the 7 other matched lung cancer tissue types (2 carcinoid, 1 carcinoma, 1 small cell, 1 small and large cell, 1 nonsmall cell, and 1 bronchoalveolar) mean Id1 expression was significantly lower in tumor as compared to matched normal tissue (P = .007)." (PMID 20414347, 2010). "Id1, which belongs to the Id family of helix-loop-helix transcription factors has been most associated with tumor progression and metastatsis; however, its significance in lung cancers has not been extensively explored." (PMID 20414347, 2010). "While our data imply a dominant role for ID1 over ID2 and ID3, purely based on the 5–10‐fold higher expression of ID1 in primary, liver, and lung cancer samples, a modest increase in ID2 and ID3 was also observed between the primary tumour and lung metastases." (PMID 40116596, 2025). "More recently, our group has shown that the combined blockade of Id1 and PD-1/PD-L1 displays synergistic therapeutic activity in KRAS-mutant lung cancer in mouse models." (PMID 37841258, 2023). "Ectopic expression of FOXA1 increased ID1, ID2, and ID3 mRNA in A549, H358, and Calu-1 lung cancer cells." (PMID 35897813, 2022). "Our results showed a higher and more dominant expression of ID1 than those of ID2, ID3, and ID4, particularly in lung cancer cell lines." (PMID 33917757, 2021). "We then examined the effect of ID1 repression in the context of EMT, using EMT genes and proteins and found similar results as those observed in PGC1α-silenced lung cancer cells." (PMID 33917757, 2021). "Here, we suggest that cooperation of TCF4-TWIST1 controlled by the PGC1α-ID1 transcriptional axis mediates EMT and lung cancer metastasis, and that this molecular framework is an attractive target for lung cancer diagnosis and treatment." (PMID 33917757, 2021). "Crizotinib decreased Id1 levels in ALK- and MET-positive lung cancer cells and inhibited cell migration." (PMID 32410828, 2020). "The BMP receptor inhibitors JL5 and DMH2 have been shown to cause a greater decrease in the expression of the BMP signaling proteins ID1, XIAP, and TAK1, and induce more cell death of lung cancer cell lines than the BMP inhibitors DMH1 and LDN." (PMID 31744505, 2019). "We provide evidence supporting that an inhibitor targeting the BMP and TGFβ type I and type II receptors will result in the greatest downregulation of Id1, TAK1, and XIAP and induction of apoptotic cell death of lung cancer cells." (PMID 27048361, 2016). "The finding that STMN3 gene is a downstream target of the ID1, and responds to signaling from nAChRs and EGFR in lung cancer cells is relevant for various reasons." (PMID 25028095, 2014). "In human lung cancer CL1-5 cells, ACVR1B (1.5-fold) and ID1 (inhibitor of DNA binding 1, dominant negative helix-loop-helix protein, 1.3-fold) were observed to be up-regulated, while LTBP3 (latent TGF-β binding protein 3, 1/1.6-fold) was down-regulated." (PMID 21998723, 2011).
lung carcinoma (continued). "Consistent with this, suppression of ID1 increased promoter occupancy of TCF4 and TWIST1 on E-box containing CDH1 and CDH2 promoter loci, and increased TCF4 and TWIST1 were observed on CDH1 and CDH2 promoters in FOXA1 knockdown A549 lung cancer cells." (PMID 35897813, 2022). "PGC1α was found to promote both ID1, ID2, and ID3 expression in lung cancer cells, suggesting that PGC1α-mediated expression of ID families might be dependent on the transcription factor that is activated by PGC1α." (PMID 35897813, 2022). "ID1, downstream of PGC1α and FOXA1, was also downregulated in TGFβ1-treated lung cancer cells." (PMID 35897813, 2022). "At present, there is no report that ID1-mediated EMT promotes the formation of tumor stem cells to regulate the immune escape of EGFR T790M-positive lung cancer." (PMID 33992097, 2021). "In addition, Id1 induces snail1expression in kidney epithelial cells and positively regulates MMP-9 expression in breast and lung cancer cell lines." (PMID 24970809, 2014). "ID1 exerts its function by acting as dominant negative transcriptional repressors of bHLH factors; we found that ID1 is up regulated in response to nicotine and EGF via nAChR and EGFR in various lung cancer cell lines." (PMID 25028095, 2014). "The Id1 staining was predominantly observed in lung cancer tissues but not in the adjacent normal lung tissues." (PMID 25344919, 2014). "A recent study identified Id1 as being differentially expressed in small cell lung cancers and went on to find elevated Id1 gene expression in tumor cells versus matched control tissues; however, no assessments were made for Id1 in nonsmall cell lung cancers." (PMID 20414347, 2010). "In the human lung cancer xenograft model, DMH1, a small molecule inhibitor of BMP signaling, markedly diminished lung cell proliferation, induced cell death, and cell migration and invasion in NSCLC cells by inhibiting p-Smad1/5/8 signaling and down-regulating Id1, Id2, and Id3." (PMID 39578779, 2024). "In addition, FOXA1 knockdown decreased ID1 and ID2 mRNA and protein levels in lung cancer cells." (PMID 35897813, 2022). "However, the levels of PGC1α, ID1, and E-cadherin in lung cancers did not decrease significantly with the tumor stage." (PMID 33917757, 2021). "Moreover, Id1 silencing also resulted in significant increased levels of surface PD-L1 expression in the murine KRAS-driven lung cancer LLC, Lacun3 and 393 P cell lines, often even without the need for a pro-inflammatory stimulus (IFN-γ exposure in this case)." (PMID 33126649, 2020). "The fact that both nicotine and EGF could induce the expression of ID1 in a Src-dependent manner raises the possibility that ID1 might be contributing to the genesis of lung cancers in both smokers and nonsmokers." (PMID 25028095, 2014). "Similarly, in our lung cancer mouse model we show that [89Zr]-anti-PD-1 uptake in tumor lesions was significantly higher among treatment-responding Id1 knock-out mice, than among non-responding mice maintaining a constitutive Id1 expression." (PMID 37841258, 2023). "However, a transcription factor that cooperates with PGC1α, which regulates ID1 and EMT in lung cancer cells, has not been identified." (PMID 35897813, 2022).
glioma (40 papers, 2012 to 2026). A benign or malignant brain and spinal cord tumor that arises from glial cells (astrocytes, oligodendrocytes, ependymal cells). "Among the newly identified direct CIC target genes were EPHA2 and ID1, whose functions are linked to neurodevelopment and the tumourigenicity of in vivo glioma tumour models." (PMID 34767259, 2022). "Finally, Id1 has been linked with glioma stem cell propagation which may contribute to increased angiogenesis since these stem-like cancer cells can differentiate in vascular endothelial cells promoting tumor angiogenesis." (PMID 24659686, 2014). "Other studies support the increase in ID1 and ID2 expression levels in H3K27-altered gliomas, either through mutations in ACVR1 and the upregulation of pSMAD1/5 in H3.1-altered gliomas or through other mechanisms in H3.3-altered gliomas." (PMID 39126064, 2024). "ID1, ID2, and ID3 allele deletions in tumors in an in situ model of brain cancer decreased the amount of glioma stem cells, halted tumor growth, and increased the survival time of mice." (PMID 38195969, 2024). "TGM2 can regulate the proliferation of glioma cells by regulating the expression of ID1 through the PI3K/AKt pathway." (PMID 37115802, 2023). "Our in vitro studies show that the anti-proliferative effect of BMP4 on glioma cells in mediated by its downstream targets, ID1 and p21." (PMID 31602000, 2019). "The first study showed that ID1 activates glioma stem cell proliferation, self-renewal, and tumorigenicity through suppression of the CULLIN3 ubiquitin ligase." (PMID 30279357, 2018). "Particularly, it was shown that ID1 inhibits differentiation signals originated from BMPR signaling in glioma stem cells to promote cell-renewal in these cells." (PMID 30279357, 2018). "In animal experimental models, ID1 overexpression of CULLIN3 knockdown stimulates glioma stem cell features and has a tumorigenic effect." (PMID 30279357, 2018). "A second study directly involved ID1 in the mechanism of BMP-mediated differentiation of glioma stem cells." (PMID 30279357, 2018). "Two recent studies have explored the molecular mechanisms through which ID1 affects the biological properties of glioma stem cells." (PMID 30279357, 2018). "Knockdown of ID1 in glioblastoma xenografts exerts a clear antitumor effect and reduces stem cell properties of glioma cells." (PMID 30279357, 2018). "In summary, we show that COX-2-dependent transformation of glioma cells is dependent on Id1 expression." (PMID 24659686, 2014). "These encouraging results prompted us to further study the potential effect of COX-2 and Id1 overexpression on in vivo growth of glioma cells." (PMID 24659686, 2014). "We next sought to achieve long-term suppression of Id1 in preparation for in vivo analysis by infecting our glioma cells with a retroviral vector expressing shRNA against Id1." (PMID 24659686, 2014). "Expression vectors containing Id1 and corresponding control were introduced into the LN229 and SF767 glioma cells and immunoblot analysis confirms significant Id1 overexpression." (PMID 24659686, 2014). "In the present study, we report that COX-2 overexpression in human glioma cells increases their expression of Id1 protein and enhances their in vitro transforming and in vivo tumorigenic potentials." (PMID 24659686, 2014). "In agreement with this, Id1 overexpression can also increase microvessel density in xenograft tumors derived from glioma cells overexpressing Id1." (PMID 24659686, 2014). "We further show that COX-2-dependent glioma transformation/tumorigenesis requires induction of Id1 and that Id1 overexpression also enhances glioma transformation/tumorigenesis." (PMID 24659686, 2014). "A more recent study found in a mouse model of gliomagenesis that a subpopulation of tumor cells displaying high levels of Id1 has high self-renewal capacity consistent with a role of Id1 in propagation of glioma stem cells." (PMID 24659686, 2014).
glioma (continued). "We found that overexpression of both COX-2 and Id1 in the LN229 glioma cell line results in a greater potential for migration in a matrigel invasion assay." (PMID 24659686, 2014). "Our results above indicate that overexpression of both COX-2 and Id1 promotes the tumorigenic potential of glioma cells." (PMID 24659686, 2014). "Assessment of Id1 overexpressors and corresponding vector only controls revealed a significant increase in the colony forming capabilities of glioma cells expressing Id1." (PMID 24659686, 2014). "COX-2 overexpression induces Id1 expression in two GBM cell lines suggesting a role for Id1 in glioma transformation/tumorigenesis." (PMID 24659686, 2014). "More importantly, knockdown of Id1 expression in glioma cells overexpressing COX-2 reduced the microvessel count in tumors derived from such cells by roughly half." (PMID 24659686, 2014). "Id1 expression in human glioma specimens has also been reported and positively correlates with tumor grade." (PMID 24659686, 2014). "In our current study, we find that overexpression of COX-2 in human glioma cells increases the malignant potential of these cells by enhancing expression of Id1." (PMID 24659686, 2014). "We first chose to test LN229 glioma cells overexpressing COX-2 or Id1 along with the corresponding vector only control (Ctr) for growth as subcutaneous tumors on the flank of nude mice." (PMID 24659686, 2014). "Our identification of Id1 as a critical factor downstream of COX-2 important for its activity in glioma cells is particularly interesting and consistent with the work of others linking COX-2 with Id1." (PMID 24659686, 2014). "Like its role in COX-2-mediated angiogenesis, Id1 is also critical for COX-2-mediated migration/invasion of glioma cells with a significant reduction in the migration of LN229/COX-2 cells when Id1 expression has been knocked down." (PMID 24659686, 2014). "Within high grade gliomas, cancer cells with high Id expression (Id1-high) had a high self-renewal capacity." (PMID 24160469, 2013). "ID1 is most expressed in glioma cells with the oligo/astrocytic precursor cell program." (PMID 39126064, 2024). "This STAT3/TRIM24/ID1 axis mediates glioma stem cell proliferation and self-renewal." (PMID 33810347, 2021). "ID1 knockdown reduces glioma invasiveness, expression of mesenchymal markers, and self-renewal." (PMID 30279357, 2018). "Interestingly, both Id1-high and Id1-low cell types are able to generate high-grade gliomas in mice, with faster tumor development and higher penetrance in the case of the low-Id1 cells." (PMID 28122577, 2017). "Interestingly, Mef was required for Sox2 and Id1 regulation in primary murine and human U87 glioma cells, both of which are important in maintaining the balance between differentiation and self-renewal." (PMID 27456282, 2016). "Thus, to elucidate the effects of RF exposure on growth, apoptosis, and malignancy of human glioma cells, we analyzed c-myc, Emp-1, bcl-2, and bax expression by real-time PCR and Id-1 protein levels by western blotting." (PMID 26253141, 2015). "Secondly, forced expression of COX-2 increases the malignancy of human glioma cells as evidenced by increased growth in vitro as colonies in soft agar and in vivo as xenograft tumors in nude mice and these effects are mainly mediated by Id1." (PMID 24659686, 2014). "Finally, COX-2 and Id1 overexpression can both increase the invasive capacity of glioma cells and promote angiogenesis in xenograft tumors derived from these glioma cells." (PMID 24659686, 2014). "Next, to establish whether PGE2 can induce Id1 in glioma cells, parental SF767 and LN229 cells were treated with increasing amounts of PGE2." (PMID 24659686, 2014). "Finally, Id1 also enhances our ability to grow out GICs, or glioma stem cells as neurospheres in tumors that overexpress this transcriptional regulator." (PMID 24659686, 2014).